E2F1 (E2F transcription factor 1)
Diseases named in the same sentence as E2F1 in open-access papers (continued):
Sharing a sentence is not in itself a finding about the gene and the disease.
leiomyosarcoma (2 papers, 2023). An uncommon, aggressive malignant smooth muscle neoplasm, usually occurring in post-menopausal women. "By integrating large-scale data, we identified two specifically deregulated pathways involved in differentiation/proliferation switch (MYOCD/SRF and E2F1/RB1) in a subgroup of well-differentiated vascular smooth muscle cell-derived cells leiomyosarcomas." (PMID 36672483, 2023). "Among the detected pathways, we identified pathways that could represent potential targets for treatment of subgroups of leiomyosarcoma patients, including RB1/E2F1 signaling, pathways involved in FGFR signaling, and CTLA4 inhibitory signaling." (PMID 37492373, 2023).
male infertility (2 papers, 2021 to 2022). The inability of the male to effect fertilization of an ovum after a specified period of unprotected intercourse. "Furthermore, this variant was predicted to alter the TFBS of E2F1, which has been previously associated with male infertility due to SPGF." (PMID 36589743, 2022). "Three genes associated with genitourinary birth defects and male infertility are MYC-associated zinc finger protein (MAZ), CRK-like proto-oncogene (CRKL), and E2F transcription factor 1 (E2F1), which are discussed in this section." (PMID 34552771, 2021).
myeloid leukemia (2 papers, 2021 to 2022). A clonal proliferation of myeloid cells and their precursors in the bone marrow, peripheral blood, and spleen. "For that, myeloid leukemia K562 cells were transduced with a lentiviral vector encoding expressing cassette where several E2F1 bind sites (BSs) linked with late adenoviral promoter (lateADEp) drive the expression of marker fluorescent protein mKATE41." (PMID 34564151, 2021). "Using GSEA, we identified the biological processes associated with high levels of E2F1 in patients with myeloid leukemia." (PMID 34564151, 2021). "Here we indicated that relatively high levels of E2F1 expression may be associated with better outcome of myeloid leukemia patients." (PMID 34564151, 2021). "Here we found that DBF is a strong inducer of apoptosis of myeloid leukemia cells and suggest that E2F1 may be a target protein, whose activity is modulated by 3,10-Dibromofascaplysin (DBF)." (PMID 34564151, 2021). "Determination of the role of TRPM2 in doxorubicin sensitivity of the myeloid leukemia cell line U937 similarly demonstrated reduced FOXM1, E2F1, and expression of proteins involved in cell cycle and DNA damage response in cells with TRPM2 deletion." (PMID 35428820, 2022).
neuroendocrine tumors (2 papers, 2010 to 2026). "In NE-10 neuroendocrine tumors where δ-catenin expression was increased, Hes1 expression was diminished and E2F1 expression was increased." (PMID 21106062, 2010).
non-alcoholic fatty liver disease (2 papers, 2020 to 2024). "It has been reported that E2F1 transcriptional activity is enhanced in obese subjects and non-alcoholic fatty liver disease." (PMID 32326181, 2020). "Protein level of E2F1 is increased in the visceral white adipose tissue of obese human subjects and is positively correlated with development of insulin resistance, circulating free fatty acids level, and incidence of non-alcoholic fatty liver disease." (PMID 32326181, 2020).
nonmelanoma skin carcinoma (2 papers, 2016 to 2017). "Abnormal E2F1 expression promotes nonmelanoma skin carcinoma." (PMID 27903963, 2017).
papilloma (2 papers, 2017 to 2020). A benign epithelial neoplasm that projects above the surrounding epithelial surface and consists of villous or arborescent outgrowths of fibrovascular stroma. "In line with this, we found that overexpression of the papilloma E7 protein had only a marginal effect on E2F1 activity in GAr-expressing cells." (PMID 29235459, 2017). "The EBNA1-mediated activation of E2F1 via MDM2 differs from other oncogenic viruses such as Simian, Human papilloma and Adeno that via Large T, E6 and E1A, respectively, compete with E2F1 for the binding to the retinoblastoma protein (pRb)." (PMID 32453417, 2020).
rectal adenocarcinoma (2 papers, 2022). "Heterozygous amplifications of ETS2 and CDK6 in TGCT; CDK6 in GBM; E2F1 and ID1 in rectum adenocarcinoma (READ); and SP1, CDK4, and MDM2 in ACC were all greater than 70%." (PMID 35911954, 2022).
rectal cancer (2 papers, 2016 to 2024). A primary or metastatic malignant neoplasm that affects the rectum. "LncRNA DLGAP1-AS2 enhanced the radiotherapy resistance of rectal cancer cells by interacting with E2F1 to increase CD151 expression through activating the AKT/mTOR/cyclinD1 signaling pathway." (PMID 39119602, 2024).
renal fibrosis (2 papers, 2022 to 2023). A final common manifestation of a wide variety of chronic kidney diseases characterized by glomerulosclerosis and tubulointerstitial fibrosis. "Interestingly, deficiency of E2F1 reduces the degree of renal fibrosis and DNA damage 80, and renal fibrosis is implicated in cell dysfunction." (PMID 36632449, 2023). "The results showed that E2F1 knockdown or metformin reduces the degree of renal fibrosis, DNA damage, and cellular senescence in the DM group; metformin also reduced the expression of E2F1." (PMID 35814218, 2022).
Testicular atrophy (2 papers, 2006 to 2022). Wasting (atrophy) of the testicle (the male gonad) manifested by a decrease in size and potentially by a loss of fertility. "E2f1-null mice display characteristics of progressive testicular atrophy that is manifested in a background strain-dependent manner implying that genetic background of the mice has an impact on the time course and severity of the phenotype." (PMID 35663332, 2022). "Similarly, ablation of either pRB or E2F1 in the germline results in progressive testicular atrophy due to germline stem cell (GSC) depletion, emphasizing the importance of proper RB-E2F interplay for germline maintenance and lifelong sperm production." (PMID 35663332, 2022).
testicular tumor (2 papers, 2006 to 2020). "In conclusion, our studies revealed the anti-cancer effect of cordycepin on FGF9-induced testicular tumor growth by affecting the expressions of p-ERK1/2, p-Rb, E2F1, cell cycle related proteins, and FGFR1-4 proteins." (PMID 33172093, 2020).
Thrombocytopenia (2 papers, 2017 to 2025). A reduction in the number of circulating thrombocytes. "Although further investigation of the molecular mechanisms involved in thrombocytopenia associated with such a gene expression profile is required, responsive mediators might be E2F-1 and Myc, which can be activated by E2F-1." (PMID 40813622, 2025). "Repressing E2f3 in E2f1−/−; E2f2−/− doubly-deficient mice triggered profound collapse of bone marrow, together with the onset of leukopenia, thrombocytopenia and progressive erythrocytopenia, with corresponding decreases in lymphocyte and myeloid cell populations." (PMID 28855541, 2017). "By three weeks post tetracycline withdrawal, E2f1−/−; E2f2−/−; E2f3TRE/TRE; β-actin-tTS mice exhibited severe leukopenia and thrombocytopenia." (PMID 28855541, 2017).
thymic lymphoma (2 papers, 2018 to 2021).
uterine corpus endometrioid carcinoma (2 papers, 2015 to 2016). "For example, an L-FFL motif constituted by E2F1, miR-15b, and IQCH-AS1, and an M-FFL motif made of E2F1, miR-15b and BCL2 formed a complex L-M-FFL motif in uterine corpus endometrioid carcinoma, but only the L-FFL motif correlated with patient survival (P=0.002)." (PMID 27322142, 2016).
acute leukemia (1 paper, 2021). A clonal (malignant) hematopoietic disorder with an acute onset, affecting the bone marrow and the peripheral blood. "There was a similarly strong correlation between High E2F1 expression and poor prognosis of acute leukemia (AL)." (PMID 33999861, 2021).
adenovirus infection (1 paper, 2022). "In order to identify the molecular mechanism responsible for the observed therapeutic effect, we first analyzed the mRNA expression of RB and E2F1 24 h after treatment with PD and adenovirus infection." (PMID 35948546, 2022). "In addition, adenovirus infection restores the siRNA-induced suppression of E2F1 24 h past infection but suppresses RB, an effect that correlates with an enhanced expression level of E1A protein 12 h past infection in E2F1 silenced cells." (PMID 35948546, 2022).
alcoholism (1 paper, 2020). "Alcoholism and smoking were observed to have profound impact on the downregulation of E2F1 mRNA expression." (PMID 32884568, 2020).
Barrett esophagus (1 paper, 2013). Esophageal lesion lined with columnar metaplastic epithelium which is flat or villiform. "In adenocarcinomas of Barrett esophagus E2F-1 overexpression was identified to be correlated with decreased proliferation and better prognosis." (PMID 24023875, 2013).
bipolar disorder (1 paper, 2021). A disorder of the brain that causes unusual shifts in mood, energy, activity levels and the ability to carry out day-to-day tasks. "This implies that targeting of GSK3β-E2F1 or NRSF signaling may be able to reduce the effects of CMS-induced bipolar disorder." (PMID 34572310, 2021).
Bloom syndrome (1 paper, 2017). Bloom syndrome (BSyn) is a rare chromosomal breakage syndrome characterized by a marked genetic instability associated with pre- and postnatal growth retardation, facial sun-sensitive telangiectatic erythema, increased susceptibility to infections, and predisposition to cancer. "Interestingly, T cell-related genes (D.3) were downregulated (Bloom syndrome, E2F transcription factor 1 and peroxiredoxin 2) in the RAG1−/− compared to the WT." (PMID 28596766, 2017).
breast adenocarcinoma (1 paper, 2022). "Overexpress of E2F1 and E2F3 were found in breast adenocarcinoma when compared to normal breast tissues." (PMID 36424626, 2022).
cataract (1 paper, 2008). Partial or complete opacity of the crystalline lens of one or both eyes that decreases visual acuity and eventually results in blindness. "E2F3a transgenic mice have small eyes and cataracts, similar to the E2F1 transgenic mice with BrdU positive fiber nuclei and enhanced programmed cell death." (PMID 18385796, 2008).
cervical tumors (1 paper, 2021). "To further study the biological effect of circZFR on E2F1 acetylation in vivo, we compared the E2F1 acetylation status in 30 cervical tumors compared to adjacent normal tissues." (PMID 33516252, 2021).
chondroid syringomas (1 paper, 2022). "Here, we further investigated the novel SRF::E2F1 fusion in myoepitheliomas, which, together with the mixed tumors/chondroid syringomas, represent a class of myoepithelial tumors of soft tissue with benign behavior." (PMID 36421692, 2022).
chronic liver failure (1 paper, 2023). Liver failure that develops slowly and gradually for some time, possibly for years, often as the result of cirrhosis, or malnutrition. "For instance, Jieduan-Niwan formula alleviates acute-on-chronic liver failure by repressing inhibiting E2F1-mediated apoptotic signaling pathways." (PMID 36777627, 2023).
chronic lymphocytic leukaemia (1 paper, 2022).
chronic pancreatitis (1 paper, 2012). A chronic inflammatory process causing damage and fibrosis of the pancreatic parenchyma. "By contrast, acinar and ductal epithelial cells from normal pancreas and chronic pancreatitis were not immunoreactive to SOX4 or E2F1." (PMID 23251334, 2012).
colorectal tumors (1 paper, 2022). "In addition, IHC analysis also showed that NCAPD3 knockout led to remarkably weaker staining of c-Myc, E2F1 and GLUT1, as well as a significant decrease of the proliferation rates of colorectal tumors in NCAPD3± mice, as evidenced by lower proportions of Ki-67 nuclear staining." (PMID 35689245, 2022).
cyst (1 paper, 2022). A sac-like closed membranous structure that may be empty or contain fluid or amorphous material. "Thus, restraining E2f1/Dp activity through Rbf is essential to allow cyst cell differentiation, such that both differentiation and cell-cycle exit are coordinated through regulation of E2f/Dp." (PMID 35545055, 2022). "Like control and Dp mutant clones, E2f1 mutant clones were composed of both Zfh1-expressing CySCs and Eya-positive differentiating cyst cells (arrows and arrowheads, respectively), suggesting that neither their self-renewal nor their differentiation capacity was altered." (PMID 35545055, 2022). "Moreover, Rbf knockdown resulted in a block of CySC differentiation, suggesting that E2f1 and Dp were indeed expressed in the cyst lineage." (PMID 35545055, 2022).
dental caries (1 paper, 2017). The decay of a tooth, in which it becomes softened, discolored, and/or porous. "Notably, NOD/SCID.e2f1-/-, a candidate humanized mouse model, may be suitable for assessing prophylaxis against dental biofilm-dependent diseases such as dental caries." (PMID 28394940, 2017).
diabetic cardiomyopathy (1 paper, 2015). Diabetic cardiomyopathy is a disorder of the heart muscle in people with diabetes. "Disease modeling and phenotypic drug screening for diabetic cardiomyopathy has revealed the potential for glucocorticoid receptor involvement, diabetic cardiomyopathy upregulation of CREB, and the E2F family transcription factors, including E2F1." (PMID 26215257, 2015).
disc degeneration (1 paper, 2023). "Besides, the deletion of p16 suppresses the down-regulation of TF E2F1/2 levels and regulates oxidative stress, thereby slowing down disc degeneration." (PMID 37915003, 2023).
ductal breast carcinoma (1 paper, 2008). "Our research suggests that E2F-1/TatHA is an effective repressor of hTERT in primary ductal carcinoma cells that are actively expressing telomerase." (PMID 18366791, 2008).
Endometrial Cyst (1 paper, 2019). It is caused by endometriosis, and formed when a tiny patch of endometrial tissue (the mucous membrane that makes up the inner layer of the uterine wall) bleeds, sloughs off, becomes transplanted, and grows and enlarges inside the ovaries.
endometriosis (1 paper, 2018). The growth of functional endometrial tissue in anatomic sites outside the uterine body. "The present study showed down-regulation of the E2F1 target miR-449 family members, which suggests that their combination possibly initiates endometriosis." (PMID 29357938, 2018).
follicular adenomas (1 paper, 2006). "We found an upregulation of E2F1 in all tumour types which is consistent with others studies, and we observed a link between E2F1 and p14ARF expression in nontumoral thyroid tissue as well as in follicular adenomas and carcinomas." (PMID 17117177, 2006).
gallstones (1 paper, 2022). Solid crystalline precipitates in the biliary tract, usually formed in the gallbladder, resulting in the condition of cholelithiasis. "The result suggested that E2F1 might be correlated with the mechanism of gallstone, and it might be a possible therapeutic target of EA." (PMID 35035504, 2022).
Giardia infection (1 paper, 2023). "Hence, we speculate that E2F1 may be regulated by E2F7 and E2F8 during Giardia infection, although the precise mechanism is still unknown." (PMID 37006313, 2023).
gynecological cancers (1 paper, 2025).
HCMV infection (1 paper, 2011). "Our data suggests a model wherein HCMV infection stimulates an E2F1-mediated DDR to activate downstream pathways that facilitate the replication or maturation of nascent virus." (PMID 21589897, 2011). "In this study, we find that HCMV infection stimulates an E2F1-mediated DDR that centers on activation of the ATM kinase early in infection and subsequently coordinates with nuclear viral replication compartments." (PMID 21589897, 2011). "Given that HCMV infection or ectopic expression of IE1 or IE2 leads to increased E2F activity, we asked whether E2F1 or other RB-associated, activator E2Fs were responsible for the DDR following HCMV infection or IE cDNA transduction." (PMID 21589897, 2011). "Therefore, HCMV infection and IE1 or IE2 expression activate an E2F1-mediated DNA damage response." (PMID 21589897, 2011). "E2F1, but not E2F2 or E2F3, promotes the accumulation of γH2AX during HCMV infection or IE protein expression." (PMID 21589897, 2011).
hemangiosarcoma (1 paper, 2025). "This aligns with our findings, where younger dogs with hemangiosarcoma, whose tumors exhibited low expression of G2/M checkpoint transcripts, including E2F1, had significantly longer survival than older dogs with tumors expressing higher levels of these genes." (PMID 40386412, 2025). "We noted E2F1 expression within the GCESS 8 cluster, suggesting a role of this regulatory pathway in hemangiosarcoma progression." (PMID 40386412, 2025).
Hepatitis (1 paper, 2010). Inflammation of the liver. "GRB2 and HSPA1A and B genes directly act on angiogenesis, TAF11 is known to be involved in artery passage, and the E2F1 transcription factor is known to be an angiogenesis positive inducer in hepatitis and cancer." (PMID 20426824, 2010).
hepatocellular adenoma (1 paper, 2007). A benign epithelial neoplasm arising from the hepatocytes.
Huntington disease (1 paper, 2019). Huntington disease (HD) is a rare neurodegenerative disorder of the central nervous system characterized by unwanted choreatic movements, behavioral and psychiatric disturbances and dementia. "Increased endogenous levels of Apaf-1 protein have been observed in human brain tumors, a consequence of E2F1 transcriptional activity, and in Huntington’s disease (HD) and its mouse and fly models." (PMID 31329620, 2019).
Hydrocephalus (1 paper, 2008). Hydrocephalus is an active distension of the ventricular system of the brain resulting from inadequate passage of CSF from its point of production within the cerebral ventricles to its point of absorption into the systemic circulation. "Knockout of genes expressed in the CPe, such as E2f5, a member of a family (E2f1–E2f6) of transcriptional regulators, FoxJ1, a member of the forkhead-box (Fox)/winged helix gene family, and p73, have been associated with hydrocephalus." (PMID 19114013, 2008). "Knockouts of E2f5, a member of a family (E2f1–E2f6) of transcriptional regulators and FoxJ1, a member of the forkhead-box (Fox)/winged helix gene family, have been associated with defective choroid plexus function resulting in hydrocephalus." (PMID 19114013, 2008).
Hypoglycemia (1 paper, 2023). A decreased concentration of glucose in the blood. "The purpose of this docking was to investigate whether the primary bioactive constituents of the compound played a role in hypoglycemia through the compound's key targets, which were CDK2, E2F1, CDKN1A, CDK1, and CCND1 and CCNB1." (PMID 36846049, 2023).